IL1B (interleukin 1 beta)
Diseases named in the same sentence as IL1B in open-access papers (continued):
Sharing a sentence is not in itself a finding about the gene and the disease.
acute pancreatitis (continued). "In addition, the latest longitudinal study found that elevated plasma levels of IL-1β and IFNγ at baseline were significant predictors of the development of new-onset prediabetes after acute pancreatitis (NOPAP) during follow-up." (PMID 35498402, 2022). "PIN significantly suppresses the production of cyclooxygenase 2 (COX-2), which is essential for inflammation, but it has also been shown to inhibit tumor necrosis factor alpha (TNF-α), interleukin 1 beta (IL-1β), and interleukin 6 (IL-6) during acute pancreatitis." (PMID 33923276, 2021). "Moreover, experimental studies have showed that administration of IL-1 receptor antagonist decreases severity of experimental acute pancreatitis, whereas overexpression of IL-1β in transgenic mice results in chronic pancreatitis." (PMID 32471279, 2020). "Obestatin, 23-amino-acid-peptide, colocalized with GHRL in human pancreas, decreased serum level of proinflammatory IL-1β and improved pancreatic blood flow in rats with cerulein-induced acute pancreatitis as well as ischemia/reperfusion-induced acute pancreatitis of rats." (PMID 29068376, 2017). "IL-1β, TNF-α, and IL-10 levels in the acute pancreatitis group were significantly increased when compared to the control negative group." (PMID 38333760, 2024). "IL-1β and TNF-α levels in the melatonin-treated pancreatitis group were significantly lower than those of the acute pancreatitis group." (PMID 38333760, 2024). "It has been suggested that proinflammatory cytokines such as IL-1β, TNF-α, and IL-6 are local and systemic mediators and play a role in the occurrence of acute pancreatitis." (PMID 38333760, 2024). "It has been shown that both NF-κB and NF-κB-regulated IL-1β, IL-6, and TNF-α expressions are related to the onset and exacerbation of acute pancreatitis." (PMID 38333760, 2024). "Studies have highlighted the crucial role of NF-κB activation in pancreatic acinar cells and the subsequent expression of IL-1β, IL-6, and TNF-α in the initiation and aggravation of acute pancreatitis through the recruitment of inflammatory cells." (PMID 38550755, 2024). "For instance, quercetin has been reported to downregulate the expression of IL-1β, IL-6, TNF-α, NF-κB, and other pro-inflammatory cytokines, alleviating acute pancreatitis." (PMID 39280954, 2022). "During acute pancreatitis, acinar cells interact with pancreatic macrophages via TNF-α, IL-1β, IL-6, and monocyte chemoattractant protein (MCP)-1 secretion, and promote the recruitment of peritoneal macrophages to pancreatic tissue." (PMID 35883885, 2022). "A clinical reported indicated that during the early acute pancreatitis stage, pancreatitis acinar cells always produced the cytokines such as tumor necrosis factor α (TNF-α) and interleukin-1β (IL-1β)." (PMID 33824873, 2021). "HBP is critical for pancreatic necrosis response in acute pancreatitis by increasing the infiltration of M1 macrophages and promoting the secretion of inflammatory factors, such as TNF-α, IL-6, IL-1β, which can be reduced by heparin." (PMID 34895060, 2021). "Over-expression of miR-9 in bone marrow-derived mesenchymal stem cells is also known to diminish the levels of IL-6, IL-1β, and TNF-α in acute pancreatitis, highlighting the critical role of miR-9 up-regulation in inhibition of inflammatory responses." (PMID 32765295, 2020). "Acute pancreatitis was enhanced in PTP1B knockout mice via increased production of inflammatory cytokines, such as IL-1β, IL-6, and TNF-α." (PMID 32760098, 2020). "By activation of the Wnt/β-catenin signal, acute pancreatitis was significantly alleviated, as is evident by the down-regulated inflammatory factors including IL-6/10, TNF, and IL-1β." (PMID 35515912, 2019). "Therefore, inhibition of IL-1β expression may prevent the development of acute pancreatitis." (PMID 29068376, 2017). "Evidences suggest that proinflammatory cytokines, such as IL-1β, TNF-α, and IL-6, act as mediators of acute pancreatitis." (PMID 29068376, 2017).
acute pancreatitis (continued). "As a consequence of acute pancreatitis, apart from hyperamylasemia, elevated production of pro-inflammatory cytokines such as TNF-α, interleukin (IL)-1β and IL-6 is often a distinctive pathological parameter." (PMID 26971398, 2016). "According to our proposed scheme, acinar cell stress in early stages of acute pancreatitis produces IL-33 and also other cytokines (e.g., TNF-α, IL-1β) that again stimulate acinar cells to release more IL-33." (PMID 23418608, 2013). "Although we measured only IL-6 and TNF, other inflammatory mediators known to play a critical role in acute pancreatitis and MODS include TNFa, IL-1b, IL-6, IL-8, platelet-activating factor, and IL-10." (PMID 20015376, 2009). "Acute pancreatitis promotes the expression of NO and inducible nitric oxide synthase (iNOS), which activates the NF-κB signaling pathway, and mediates the increase induced by spinal cord cyclooxygenase-2 (COX-2) via IL-1β, and stimulates pain in the body." (PMID 40411704, 2025). "Furthermore, in an acute pancreatitis mouse model, 1,8‐cineole administration resulted in lower cytokine levels of TNF‐α, IL‐1β, and IL‐6, reflecting the results found with thalidomide, a TNF‐α inhibitor." (PMID 40719271, 2025). "Disulfiram effectively suppressed the cleavage of GSDMD, ameliorated the development of caerulein‐induced severe acute pancreatitis (SAP) and the corresponding lung injury, and notably attenuated the expression levels of the pro‐inflammatory cytokines IL‐1β and IL‐18." (PMID 40801277, 2025). "IL-1β and TNF-α act locally and exacerbate acute pancreatitis." (PMID 38333760, 2024). "Therefore, preventing the release of inflammatory factors IL-6, IL1-β, and TNF-alfa is an important research direction to prevent the progression of acute pancreatitis." (PMID 36611865, 2022). "Besides, it also investigated the effect of XCHD on the generation of IL-6, IL-1β, and TNF-α in an LPS-induced acute pancreatitis model." (PMID 33824873, 2021). "Since that acute pancreatitis is an inflammatory disorder of the pancreas, we have also detected that VB 12 reduced the level of MPO in the AP model in vivo and reduced the level of inflammatory factors IL-1β and TNF-α in the supernatant of acinar cell culture in vitro." (PMID 34925701, 2021). "During experimentally induced systemic inflammatory conditions (e.g., acute pancreatitis and acute hepatitis) Lac may downregulate Toll-like receptor 4, NLRP3 (NACHT, LRR, and PYD domains-containing protein 3) inflammasome, and concomitantly IL-1β." (PMID 28499395, 2017).
brain injury (77 papers, 2006 to 2026). Acute and chronic (see also brain INJURIES, CHRONIC) injuries to the brain, including the cerebral hemispheres, CEREBELLUM, and brain STEM. "In various in vitro experiment models, inflammatory factors, such as TNF-α, IL-1β, and IL-6, have been shown to be associated with CI-induced brain injury." (PMID 34867377, 2021). "IL-6 contributes to tissue repair after ischemic brain injury and IL-23 exerts neurotoxic effects during early-phase IS, while the loss of IL-1β function reduces infarct size." (PMID 24991091, 2014). "Up-regulated expression of Na-K-Cl Cotransporter 1 (NKCC1) and inflammatory mediators such as tumor necrosis factor alpha (TNF-α) and interleukin-1 beta (IL-1β) has been demonstrated to be closely associated with the pathogenesis of cerebral edema resulting from a variety of brain injuries." (PMID 24916922, 2014). "In traumatic brain injury, antibodies against IL-1β reduce the loss of hippocampal neurons." (PMID 22200088, 2011). "A previous study found that IL-1β levels decreased after treatment with celecoxib and ibuprofen following traumatic brain injury (TBI) in male rats." (PMID 41404029, 2025). "In an analogous manner, we now show that brain injury converges on TAM Ccl5 production through a different mechanism involving neuronal glutamate-induced oligodendrocyte IL-1β secretion, a key immunomodulator of brain injury." (PMID 38308315, 2024). "Brain injury results in an increase in dsDNA in the blood, causing AIM2 inflammasome activation in blood monocytes and IL-1β release, which subsequently induces FAS ligand (FASL)-FAS-dependent T cell apoptosis leading to immunosuppression." (PMID 37216118, 2023). "Studies proved that interference with NLRP3 inflammasome activation and IL-1β secretion effectively ameliorated the brain injuries." (PMID 35077922, 2022). "We next evaluated the efficacy of D-DPTIP in a murine acute brain injury model where intra-striatal IL-1β injection induces EV release into plasma." (PMID 36297501, 2022). "Epo has been extensively studied in NE as a potential therapeutic agent, as it decreases leucocyte infiltration and prevents IL-1β rise post-exogenous administration in animal models of brain injury." (PMID 34712631, 2021). "The active NLRP3 inflammasome cleaves proinflammatory IL-1β to its active form, which is a key determinant of outcome after brain injuries." (PMID 34489645, 2021). "Previous studies also show that cooling is accompanied by a reduction in TNF-α, IL-6, and IL-1β expressions in the setting of ischemic brain injury and neuroinflammation." (PMID 34776788, 2021). "Pro-inflammatory cytokines, such as TNF-α, IL-1β, and IL-6, are produced in the central nervous system and exert great effects on neuroprotection, which have been proven to be elevated in traumatic brain injury." (PMID 33791290, 2020). "There is substantial evidence that pro-inflammatory cytokines, TNF-α, IL-1β and IL-6 can operate at very low concentrations on many cell types in the CNS or periphery, and can contribute to neurodegeneration in acute brain injury." (PMID 30682785, 2019). "Consistently, FN attenuated neuroinflammatory reaction through downregulating TNF-α and IL-1β and upregulating IL-10 in a rat model of traumatic brain injury." (PMID 31561418, 2019). "Elevated brain protein levels of TNF-α, IL-1β and IL-6 have also been detected in human CSF and serum after brain injuries." (PMID 30682785, 2019). "IL-1β, one of the proinflammatory cytokines, is an important mediator of brain injuries/stress, and its role in the induction of MMP-9 has been well documented." (PMID 27795859, 2016). "Consistent with pharmacological inhibition of P2X7R, a significant reduction in IL-1β expression following experimental brain trauma/stress was observed in the cortex of P2X7 knockout mice, when compared with wild-type mice." (PMID 27795859, 2016).
brain injury (continued). "In conclusion, our study explored the mechanism of ATP/P2X7R signaling in the disruption of BBB following brain trauma/stress injury, especially focusing on the relationship with IL-1β and MMP-9." (PMID 27795859, 2016). "Individuals affected with PTSD exhibit altered expression of molecules involved in immune activation while brain trauma alters release of cytokines such as interleukin-1β (IL-1β) and IL-10." (PMID 23483949, 2013). "Such ability of neurons to produce IL-1β mRNA and protein has also been shown by previous studies using either rodents subjected to HI, traumatic, and excitotoxic brain injuries, or samples of lesioned human perinatal brains." (PMID 24007297, 2013). "The synthetic cannabinoid, dexanabinol, which facilitated recovery and decreased cell death, reduced hippocampal expression of TNFα and IL-1β in the hippocampus after traumatic brain injury." (PMID 22537429, 2012). "Pro-inflammatory cytokines such as interleukin-1 beta (IL-1β) are considered to exert detrimental effects during brain trauma and in neurodegenerative disorders." (PMID 22200088, 2011). "This ACh subsequently acts on α-7 nicotinic acetylcholine receptors (α-7nAChR), predominantly expressed on macrophages, leading to a reduction in pro-inflammatory cytokines such as TNF-α, IL-1β, and IL-6, thereby facilitating the recovery of neurological function following acute brain injury." (PMID 39723424, 2024). "However, upon brain injuries, MGs became active and highly proliferate due to several factors (e.g., IL-1β, IL-4, Tnf-α, and GM-CSF)." (PMID 36675286, 2023). "Indeed, the levels of proinflammatory cytokines such as TNF-α, IL-1β, and IL-6 were significantly elevated in the early stage after brain injuries." (PMID 35163096, 2022). "However, following ischemic brain injury, the expressions of IL-1β and TNF-α were drastically increased in the microglia in the ipsilateral region, as shown by combined FACS and qPCR." (PMID 35968363, 2022). "Previous studies have identified that CRID3 can inhibit ASC oligomerization in response to the stimulation of inflammasomes and further inhibit caspase-1 processing, IL-1β secretion, and pyroptosis in murine models of traumatic brain injury, dermal and pulmonary inflammation." (PMID 32861243, 2020). "Furthermore, they can secret proinflammatory cytokines such as TNF-α, IL-1β and IL-6 to recruit other immunocytes such as neutrophils and lymphocytes, which further aggravate brain injuries." (PMID 26086994, 2015). "Similar reductions in Il1β were observed after lovastatin treatment on rat primary microglia and in vivo in a rat model of simvastatin treatment following traumatic brain injury, though a recent study found simvastatin treatment increased secretion of Il1β from isolated primate microglia." (PMID 25424483, 2014). "Moreover, the n-3 deficiency primed the immune system to the challenges imposed by the WD and brain trauma as evidenced by results showing that the WD or mTBI affected brain IL1β levels and peripheral Th17 and Treg subsets only in animals previously conditioned to the n-3 deficient diet." (PMID 23483949, 2013). "This study, to our knowledge, is the first time to show that the increased expression of IL-1β, IL-6, and TNF-ɑ genes on days 3 and 7 after brain trauma can be inhibited remarkably by propofol administration." (PMID 39810851, 2024). "In this regard, specific proinflammatory cytokines, including IL-1β, IL-6, TNF-α, and IFN-γ, and markers of brain injuries, such as NFL and GFAP, have been proposed as etiological factors of SB/SI development." (PMID 38338174, 2024). "In an acute brain injury model, orally administered D-DPTIP significantly reduced the intra-striatal IL-1β-induced increase in plasma EVs up to 72 h post-dose, while oral DPTIP had a limited effect." (PMID 36297501, 2022). "The levels of IL-1β are one of the most frequently evaluated inflammatory factors in TBI research and have been shown to increase following brain injury." (PMID 35346242, 2022).
brain injury (continued). "That is, TLR4 and C5aR1 represent an alternative upstream regulator in activating NF-κB by inhibiting cAMP/PKA signals and participate in TNF-α, IL-1β, and IL-6 production in MCAO/R-induced brain injury." (PMID 33633530, 2021). "Brain injury induces the activation of M1 microglia and releases proinflammatory cytokines, such as TNF-α, IL-1β, and IL-6." (PMID 32922507, 2020). "The inflammatory markers, such as microglia, ROS, IL-1β, and TNF-α, were detected in patents who experienced brain injuries." (PMID 29747437, 2018). "Additionally, it has been hypothesized that IL-1β may induce SNS activation after brain trauma." (PMID 26883121, 2016). "Compared to the ~2-fold increase in IL-1β, there was a ~6-fold increase in IL-6 expression after TBI implying that this protein, among others, is more central to the inflammatory response in brain trauma." (PMID 27199506, 2016). "Gut barrier dysfunction and enhanced translation of NF-κB, TNF-a, IL-1b, IL-6, and ICAM-1 were observed in Nrf2−/− mice after traumatic brain injury." (PMID 27009867, 2016). "For example, in a rat Marmarou model of diffuse brain injury, TNF production is of a higher magnitude, and IL-1β expression is heightened and prolonged, when the injury is followed by a 30-min period of hypoxia." (PMID 23459929, 2013). "Together with IL-1β and IL-6, TNF-α is one of the major pro-inflammatory cytokines released by activated microglia following ischemic brain injury." (PMID 17150094, 2006). "Clemastine, as an antihistamine, has a positive anti-neuroinflammatory effect, could reduce the activation of microglia and down-regulate the expression of IL-1β and NLRP3 in rats with hypoxic-ischemic brain injury." (PMID 34497527, 2021). "Interestingly, in traumatic brain injury (TBI) which shares some pathological sequalae to our model, IL-1β is also upregulated in the brain as early as three hours after injury." (PMID 31774879, 2019). "In the present study, the IL-1β stimulation triggered an elevated level of GFAP and induced the astrocyte hypertrophy; this phenomenon was confirmed by the lesion site in a traumatic brain injury." (PMID 28356158, 2017). "Inflammatory mediators, including IL-1β, IL-6, IL-10, TNF-α and NF-κB were assessed to examine whether GLGZD was involved in the inflammatory response in ischemic brain injury." (PMID 25815894, 2015). "Notably, HFD in the presence of TBI showed significant diet*injury interactions with exacerbation of HFD-dependent increases in VAT pro-inflammatory molecules IL-1β and NLRP3, indicating a brain trauma-dependent amplification of diet-induced adipose tissue inflammation." (PMID 38685031, 2024). "After ischemic brain injury, for example, combined blockade of both IL-1α and IL-1β is necessary for maximal protection, whereas neuroprotection after spinal cord injury is achieved by selective IL-1α, but not IL-1β, blockade." (PMID 29662944, 2018). "IL-1β is known to strongly enhance inflammatory responses following TBI, and this has led many to postulate that IL-1 production may negatively impact clinical outcomes following brain trauma." (PMID 27994591, 2016). "Indeed, processing of pro-IL-1β followed by secretion of the mature protein has been proposed as the mechanism for the rapid release of IL-1β independent of de novo protein synthesis following traumatic brain injuries." (PMID 22615852, 2012). "Moreover, IL-1β-induced ROS signal and MMP-9 expression in brain astrocytes imply that IL-1β-mediated redox signals and MMP-9 induction may be vital for the development of brain injuries and inflammatory diseases." (PMID 35740292, 2022).